ALK (ALK receptor tyrosine kinase)
Diseases named in the same sentence as ALK in open-access papers (continued):
Sharing a sentence is not in itself a finding about the gene and the disease.
prostate carcinoma (43 papers, 2012 to 2025). A carcinoma that arises from epithelial cells of the prostate gland. "Further, in neuroendocrine prostate cancer (NEPC), a severe form of prostate cancer, a mutation (ALK F1174C) in the ALK gene responded well to alectinib." (PMID 38397899, 2024). "ALK overexpression was associated with a distinct transcriptional profile and adverse clinical outcomes in patients with advanced prostate cancer." (PMID 36337169, 2022). "Similarly, cyclinD1 has been repeatedly associated with the aggressiveness of prostate cancer and its tendency to cause bone metastases, while the overexpression of ALK has been observed in advanced prostate tumors." (PMID 39120316, 2024). "A previous study reported that the first-generation ALK-targeted compound crizotinib could prevent prostate cancer-associated bone loss." (PMID 36425467, 2022). "A recent case report demonstrated a clinical response to the second-generation ALK inhibitor alectinib in a patient with de novo NEPC harboring an ALK p.F1174C activating mutation, suggesting that targeting ALK could be relevant in selected patients with prostate cancer." (PMID 36337169, 2022). "Other prostate cancer-associated somatic mutations were consistent in some PDOs and parental tumours, such as BRCA1, ALK, STED2, TET2, TRPM8, AURKA, ERBB2, GATA2." (PMID 41403018, 2025). "Among 372 primary prostate cancer cases, we identified one case with uniformly high ALK protein expression." (PMID 36337169, 2022). "In our cohort of 372 localized prostate cancers, we identified a single case with strong and uniform ALK expression." (PMID 36337169, 2022). "We show that ALK overexpression is present in advanced prostate cancers, in particular in cases with features of neuroendocrine carcinoma." (PMID 36337169, 2022). "In summary, the data presented here demonstrate that a subset of prostate cancers show potentially actionable alterations of the tyrosine receptor kinase ALK." (PMID 36337169, 2022). "To identify prostate cancer models with high ALK expression, we assessed ALK protein levels in cell lines and patient-derived xenografts." (PMID 36337169, 2022). "On the basis of this result, it is likely that rare, oncogenic ALK alterations represent oncogenic drivers in prostate cancer that can be targeted by available ALK inhibitors." (PMID 36337169, 2022). "Our study demonstrates that ALK-directed therapies should be considered in selected prostate cancer cases." (PMID 36337169, 2022). "For two of these three patients (prostate carcinoma and ALK-fusion-positive DLBCL), the MTB suggested SoC treatment." (PMID 36139590, 2022). "In summary, we found that ALK overexpression is rare in primary prostate cancer, but more frequent in metastatic prostate cancers with neuroendocrine differentiation." (PMID 36337169, 2022). "Although ALK expression was uncommon in primary prostate cancers, we identified one case with high-level ALK protein expression due to a novel structural rearrangement involving SLC45A3 and ALK." (PMID 36337169, 2022). "Although prostate cancer has not been thought of as an ALK-driven tumor, anecdotal evidence suggests that ALK genomic and expression alterations can be observed in prostate cancer." (PMID 36337169, 2022). "In our expanded survey of advanced metastatic prostate cancers, we observed increased ALK expression in a subset of prostate cancer metastases." (PMID 36337169, 2022). "(EGFR and ALK in NSCLC, BRCA1 and BRCA2 in breast and ovarian cancer and homologous recombinant deficiency in prostate cancer)." (PMID 35047063, 2021). "Whilst ALK fusions are associated with poor prognosis, they have not been extensively studied in prostate cancer." (PMID 39217195, 2024).
prostate carcinoma (continued). "ALK fusions with DCTN1 or other lysosome trafficking proteins may impair lysosomal traffic and maturation, promoting increased ALK signalling through perturbed lysosomal degradation, facilitating prostate cancer development." (PMID 39217195, 2024). "Interestingly, the first generation ALK inhibitor crizotinib has been reported to inhibit osteoclast formation and prevent prostate cancer bone destruction." (PMID 36425467, 2022). "Collectively, our data suggest that targeting ALK could be considered in a selected subset of patients with advanced prostate cancers." (PMID 36337169, 2022). "Our data suggest that ALK-directed therapies could be an option in selected patients with advanced prostate cancer." (PMID 36337169, 2022). "Here we delineate the spectrum of ALK alterations in prostate cancer." (PMID 36337169, 2022). "Together, these studies support the notion that prostate cancers with increased ALK expression or putative driver genomic alterations might be sensitive to pharmacologic ALK inhibition." (PMID 36337169, 2022). "From the 303 biopsies with adequate tumour content (tumour cellularity ≥ 10%), 159 (52.5%) were included in cohort 1 (Global Match-R), 12 (4%) in cohort 2 (NSCLC EGFR + /ALK+), 57 (18.8%) in cohort 3 (Immunotherapy) and 75 (24.8%) in cohort 4 (Prostate cancer)." (PMID 32964129, 2020). "The discovery of recurrent ETS-family translocations in prostate cancer, a RAF kinase gene fusion in ETS-negative prostate cancer, and an ALK kinase fusion in lung cancer further advocates the significance of gene fusion events in the development of epithelial cancers." (PMID 23072312, 2012). "However, little is known about ALK alterations in a broader spectrum of prostate cancers." (PMID 36337169, 2022). "Collectively, these experiments provide evidence that ALK-overexpressing prostate cancers can be targeted with small-molecule ALK inhibitors and suggest that ALK inhibitors might represent a potential therapeutic option for advanced prostate cancers with high ALK expression." (PMID 36337169, 2022). "In summary, these data demonstrate that a subset of advanced prostate cancers, which are enriched for NEPC, show high level of ALK expression that is readily detectable by a validated IHC assay." (PMID 36337169, 2022). "Although some patients were treated for advanced HER2+ and triple‐negative breast cancer, advanced prostate cancer, and ALK and ROS1 NSCLC, experts deemed them unrepresentative in terms of healthcare resource utilization." (PMID 40740130, 2025). "Prolactin receptor (PRLR), which has been suggested as a therapeutic target in subgroups of breast and of prostate cancer, was overexpressed in EGFR-positive tumors compared to ALK/EGFR-negative tumors and compared to ALK-positive tumors (FC = 3.8, p = 0.0004 and FC = 2.6, p = 0.013)." (PMID 34125345, 2022). "Indeed, we found that the number of clusters expressed by specific combinations of either intra-vesicular (STAT3 and CyclinD1) or surface proteins (ERBB3, ALK, and CD81) allowed us to significantly discriminate the patients with prostate cancer from the individuals with hyperplasia." (PMID 39120316, 2024). "The identification of recurrent gene fusions in common epithelial cancers—for example, TMPRSS2/ERG in prostate cancer and EML4/ALK in nonsmall cell lung carcinomas—has raised the question of whether fusion genes are pathogenetically important also in ovarian carcinomas." (PMID 24504521, 2014). "Given the highly favorable expression pattern of ALK with no/limited detectable protein expression in benign tissues, antibody–drug conjugate or cell-based therapies exploiting the cancer-specific expression of ALK could be attractive options for prostate cancer." (PMID 36337169, 2022).
small cell lung carcinoma (43 papers, 2017 to 2026). Small cell lung cancer (SCLC) is a highly aggressive malignant neoplasm, accounting for 10-15% of lung cancer cases, characterized byrapid growth, and early metastasis. "One hundred and thirty-three patients with small cell lung cancer or NSCLC that was treated with targeted therapy against an EGFR mutation or ALK translocations were excluded from the analysis, leaving 667 patients." (PMID 34518623, 2021). "ALK (C1156Y) is a mutation of the ALK tyrosine kinase, which has been associated with acquired resistance to the targeted ALK inhibitor, crizotinab, used for the treatment of small cell lung cancer." (PMID 31816878, 2019). "Considering the promising results in small-cell lung cancers, the application of ALK inhibitors deserves to be tried." (PMID 41007824, 2025). "Anaplastic lymphoma kinase (ALK) gene rearrangement-positive small-cell lung cancer (SCLC) is extremely rare." (PMID 39781173, 2024). "Another form of histologic transformation is the conversion of adenocarcinoma to small-cell lung cancer following the initiation of ALK TKI." (PMID 38835344, 2024). "Many cases have reported drug resistance due to the conversion to small cell lung cancer (SCLC) or squamous cell carcinoma (SCC) after targeted therapy against ALK-positive adenocarcinoma." (PMID 34660278, 2021). "We also included ALK-G1269A, which represents a resistant mutation reported in an EML4-ALK fusion protein in a non-small-cell-lung-cancer cases." (PMID 31334113, 2019). "Another recently identified mechanism of resistance against ALK TKIs is the histological transformation from a NSCLC entity to Small Cell Lung Cancer (SCLC)." (PMID 29495603, 2018). "PLEKHM2-ALK: a novel fusion in small-cell lung cancer and durable response to ALK inhibitors." (PMID 40136367, 2025). "Our case showed that next-generation ALK-tyrosine kinase inhibitors (TKIs) may be an appropriate choice after transformation to small cell lung cancer and failure to one ALK-TKI." (PMID 38961982, 2024). "Currently, only a few cases of small cell lung cancer (SCLC) harboring the EML4-ALK fusion gene have been reported, yet the potential of ALK inhibitors to treat these cases remains a topic of significant interest." (PMID 40136367, 2025). "Indeed, ALK rearrangements may still exist in the current patient's small cell lung cancer tissues." (PMID 38961982, 2024). "We use the keywords “small cell lung cancer”, “SCLC”, “EGFR”, “ALK”, “histological transformation”, and “transcriptional factors” to identify original research manuscripts, clinical trials, case reports, and case series from PubMed." (PMID 38203395, 2023). "ALK-independent resistance mechanisms involve bypass pathways, such as EGFR, cMET, and AXL, or histological transformation into small cell lung cancer (SCLC)." (PMID 35463328, 2022). "NSCLC also acquire resistance through transforming to a small cell lung cancer (SCLC) phenotype, although given that these cells retain their ALK rearrangements, further investigation is required to determine why these transformations mediate resistance." (PMID 34885113, 2021). "Thus, the series of second- and third-line EGFR or ALK TKIs is eventually rendered inactive by activation of alternative kinases and, in the case of NSCLC, by a histological switch to a small cell lung cancer (SCLC) phenotype, which is not susceptible to the original TKIs." (PMID 35582610, 2020).
rhabdomyosarcoma (42 papers, 2014 to 2026). A rare aggressive malignant mesenchymal neoplasm arising from skeletal muscle. "In contrast, our case was negative for myogenic markers such as desmin, caldesmon, calponin, and MyoD1, as well as for the IMT-associated marker ALK, supporting the exclusion of leiomyosarcoma, rhabdomyosarcoma and IMT." (PMID 40936706, 2025). "Next-generation sequencing (NGS) targeting 1,267 genes identified a rare novel rhabdomyosarcoma 2-associated transcript (RMST)-ALK translocation (R5′UTR: A20) and an ALK-intergenic (A19: intergenic) rearrangement." (PMID 35978810, 2022). "The differential diagnosis with the solid variant of alveolar rhabdomyosarcoma, especially those examples showing ALK-positive, can also be difficult." (PMID 26178751, 2015). "An example of this is the frequent coexpression of pankeratin and ALK in FET::TFCP2 fusion aggressive rhabdomyosarcomas and the frequent expression of EMA and keratins (in addition to occasional ALK, MUC4, etc.)in FET::CREB fusion intra-abdominal neoplasms." (PMID 39249507, 2024). "The first successful cloning of full-length ALK cDNA utilized a cDNA library from an Rh30 rhabdomyosarcoma cell line and further studies have confirmed its presence in certain rhabdomyosarcoma tumors." (PMID 38339401, 2024). "The full-length ALK cDNA was originally cloned from the Rh30 rhabdomyosarcoma cell line and its expression has been confirmed in the alveolar subtype of primary rhabdomyosarcoma." (PMID 33466277, 2021). "Rhabdomyosarcoma is also known to show ALK aberrations, but these are different from the translocation; in a preclinical trial an ALK inhibitor seemed to be inactive against rhabdomyosarcoma." (PMID 29510588, 2018). "Furthermore, ALK is expressed on the cell surface of rhabdomyosarcomas harboring a PAX3 or PAX7::FOXO1 fusion (fusion-positive rhabdomyosarcoma), the most common soft tissue sarcoma of childhood and adolescence." (PMID 40813394, 2025). "It encompasses variably myxoid entities including acral fibromyxomas, extraskeletal myxoid chondrosarcoma, ganglion cyst with mucus extravasation, ALK + epithelioid cell histiocytoma, ALK-rearranged myxoid dermal neoplasms, ALK-positive fusion-driven rhabdomyosarcoma and other myxoid lesions." (PMID 40748380, 2025). "ALK is a lineage-restricted oncoprotein expressed on the cell surface of NBL as wild-type (WT), mutated, or amplified kinase, and recently shown to be overexpressed in fusion-positive rhabdomyosarcoma (RMS)." (PMID 38804307, 2024). "Vesicular rhabdomyosarcoma: often ALK-positive, but lacks fibrovascular stroma." (PMID 39703852, 2024). "The target candidates for rhabdomyosarcoma have included the RAS-signaling pathway, ALK, NTRK, FGFR, and MSI-High." (PMID 41749943, 2026). "ALK is highly expressed in pediatric rhabdomyosarcoma, and high sensitivity of RMS to the ALK inhibitor has been found in vitro." (PMID 38090056, 2023). "ALK fusions were identified in about 50% of IMT cases, 3.6% of sarcomatous malignancies, and extremely rare in rhabdomyosarcomas and leiomyosarcoma." (PMID 34722239, 2021). "Kinase targets found in the analysis were for osteosarcoma (KIT), Ewing’s sarcoma (ALK), undifferentiated pleomorphic sarcoma (JAK2, ABL2), alveolar rhabdomyosarcoma (NTRK1), and leiomyosarcoma (ALK)." (PMID 29541442, 2018). "Rhabdomyosarcoma (RMS) is an aggressive childhood cancer where emerging therapies rely on the use kinase inhibitors, and among druggable kinases ALK represents a potential therapeutic target to commit efforts against." (PMID 26147305, 2015). "For example, while alterations in ALK tend to be gene fusions in STS, ALK alteration in rhabdomyosarcoma is mainly amplification, thus the investigated ALK inhibitor crizotinib is not effective for rhabdomyosarcoma." (PMID 35586877, 2022).
ovarian carcinoma (39 papers, 2013 to 2025). A malignant neoplasm originating from the surface ovarian epithelium. "In human ovarian cancer tissue samples, expression of p-ALK was associated with resistance to PARP inhibitors and platinum-based (cisplatin/carboplatin) chemotherapy." (PMID 36253486, 2022). "ALK is overexpressed in ovarian cancer and associated with an aggressive, metastatic phenotype." (PMID 36495366, 2023). "Moreover, p-ALK expression was also associated with shorter overall survival in patients with ovarian cancer treated with platinum-based chemotherapy." (PMID 36253486, 2022). "Collectively, these data indicated that ALK is an important therapeutic target for overcoming PARP inhibitor resistance in ovarian cancer and TNBC." (PMID 36253486, 2022). "Next, we evaluated the individual and combined effects of PARP and ALK inhibitors in vivo by utilizing ovarian cancer xenograft models and tumor xenograft models of TNBC with acquired resistance to PARP inhibitors." (PMID 36253486, 2022). "BMP4 in ovarian cancer cells induces EMT via the (BMP4)/anaplastic lymphoma kinase (ALK) pathway, increasing the expression of mRNA and protein levels of Snail and Slug and downregulating E-cadherin." (PMID 26356073, 2015). "Targets such as HRD, BRAF, RET, HER2, and PD‐1/PD‐L1 have also emerged on the stage, but seldom research indicates that ALK inhibitors may be effective in the treatment of EML4‐ALK+ ovarian cancer." (PMID 39780907, 2025). "This may be the first clinical evidence of LGSO benefit from ALK inhibitors, to provide evidence for the use of ALK inhibitors in more ovarian cancer patients with EML4‐ALK fusion and promoting new ideas for the study of EML4‐ALK targets in ovarian cancer." (PMID 39780907, 2025). "This body of research not only underscores the pivotal role of SOX3 in ovarian cancer but also connects it with other key molecular players like ALK, offering a better understanding of the molecular underpinnings of ovarian cancer and highlighting potential targets for therapeutic intervention." (PMID 38927713, 2024). "Of note, no ovarian cancer patients within any stratum exhibited ALK rearrangement, BRAF, EGFR, or KIT mutations." (PMID 25593979, 2014). "We also found that in 79 samples (of which 62 were central nervous system (CNS) tumors, seven were ovarian cancers, five were NSCLC, and five were other cancers), all ALK exons were transcribed, indicating the increased expression of the wild-type gene." (PMID 39594806, 2024). "It is of interest that we observed a positive correlation between p-ALK- and p-Tyr19-CDK9 in patients with ovarian cancer." (PMID 36253486, 2022). "Mice bearing ovarian cancer xenografts treated with PARP and ALK inhibitors had reduced tumor growth compared with those that received either drug alone." (PMID 36253486, 2022). "Another recent evidence demonstrated that the ovarian high-grade serous carcinoma (HGSC) had significantly higher cytoplasmic ALK expression without chromosomal rearrangement or gene alterations compared to non-HGSC ovarian carcinomas." (PMID 36145589, 2022). "Finally, variants in the genes ROS1, NOTCH1, ALK, KMT2D, and SPOP have to our knowledge not previously been reported in ovarian cancer." (PMID 28611940, 2017). "The low percentage of HER2 positive ovarian cancer cases may be among the reasons why routine HER2 testing is not performed, however NSCLC adenocarcinoma cases are increasingly sent for ALK testing even though the prevalence of ALK positivity is estimated to be only about 5%." (PMID 23289505, 2013).